FOXP3 (forkhead box P3)
Diseases named in the same sentence as FOXP3 in open-access papers (continued):
Sharing a sentence is not in itself a finding about the gene and the disease.
tumor (continued). "We could therefore suggest that patients with a favorable prognosis have a well-differentiated early-stage tumor that is largely infiltrated with immunosuppression-incompetent FoxP3+ Tregs." (PMID 30781400, 2019). "The combined treatment significantly inhibited tumor growth by continuously eliminating Foxp3+ regulatory T cells and myeloid-derived suppressive cells, dramatically decreasing the infiltration of tumor-infiltrating lymphocytes, and reducing the expression of PD-1 and PD-L1." (PMID 31905724, 2019). "In addition, CCL20 mRNA expression was positively correlated with FOXP3 expression in tumor tissues (r = 0.323, P = .04)." (PMID 31852159, 2019). "Additionally, deficiencies in Treg TRAF6 expression lead to reduced FOXP3+ T‐cell frequencies within the CD4+ T cells infiltrating several lymphoid and tumor tissues." (PMID 30886050, 2019). "In addition, FoxP3+ Tregs help tumor cells grow and metastasize through production of protumorigenic cytokines and expression of immunomodulatory receptors that suppress immune response and facilitate tumor growth." (PMID 31075939, 2019). "The short distance between CD8+ and FOXP3+ cells has been hypothesized to be related to poor prognosis, as tumor-specific CD8+ T immune responses were suppressed by Tregs." (PMID 30999966, 2019). "Finally, given the central role FOXP3+ Treg cells play in maintaining immune tolerance within both the allograft and the tumor, we sought to determine how Treg cellular dynamics were changed under ICI-mTORi combination treatment." (PMID 31624262, 2019). "Notably, PD-1 was higher in tumor-infiltrating Foxp3+Treg cells (~ 98%) than in Foxp3−Tconv cells (~ 82%) or CD8+ Tconv cells (78%)." (PMID 31801611, 2019). "HHLA2 overexpression was associated with sparser CD3+ tumor infiltrating lymphocytes (TILs), CD8+ TILs and a higher CD4 + Foxp3+/CD8+ TIL ratio, whereas PD-L1 expression was associated with prominent T cells and CD163+ tumor associated macrophages infiltrations." (PMID 30885276, 2019). "Prevalence of T-regs (CD4+CD25+FOXP3+) in peripheral blood and tumor infiltrating of HCC patients lead to an unfavorable prognostic, promote disease progression and may prevent effective antitumor immune responses." (PMID 31653148, 2019). "Moreover, low concentration of IL-24 promoted FoxP3 mRNA expression in tumor-infiltrating CD4+ T cells (Tukey test, P = 0.012)." (PMID 31921658, 2019). "Indeed, only a weak correlation between the density of Foxp3+Tbet– Tregs and these tumor-infiltrating Tbet+ T cell subtypes was observed." (PMID 30658697, 2019). "T cell infiltration and frequency of FOXP3+ Tregs, MDSCs, and tumor-associated macrophages all have been discussed in the literature as predictors of OS in specific tumor types, but none were analyzed across multiple types of tumors." (PMID 31208461, 2019). "In light of this and our other findings, the development of therapeutic TRAF6 inhibitors may yield highly effective agents for sabotaging this posttranslational mode of regulating FOXP3 activity and fully unleashing the anti‐tumor immune response." (PMID 30886050, 2019). "Furthermore, the number of PD-1-expressing tumor-infiltrating Foxp3+ Treg cells was greater than the number of tumor-infiltrating Foxp3+ Treg cells expressing other IC-molecules." (PMID 31801611, 2019). "Also, HLA-1 low-expressing tumor areas appeared to frequently be surrounded by a greater number of CD4+FOXP3+ (regulatory T cells) and a lower number of CD68+ (likely macrophages) immune cells relative to HLA-1 high-expressing tumor regions of the same TME." (PMID 31166985, 2019). "Th17 cells also might be a source of tumor-induced FoxP3+ cells besides nTreg and iTreg cells which have developed from naïve CD4+ precursors." (PMID 31024835, 2019). "We then examined whether SM16 diet exerted an inhibitory effect on primary tumor growth and correlated with changes in FoxP3+expression." (PMID 31288845, 2019).
tumor (continued). "Interestingly, both rMVA and rMVA-CD40L single immunizations decreased the percentage of FoxP3+ Treg in the tumor microenvironment." (PMID 31695037, 2019). "Future studies may address the different roles of different Foxp3 methylation regions on Treg biology and their functionality on tumor growth." (PMID 31006654, 2019). "For instance, clinical infusion of EGFRvIII-directed CAR-T cells for the treatment of glioblastoma resulted in influx of CD4+CD25+FoxP3+ cells in the tumor, whereas CD19-targeted CAR-T cells against B-cell lymphoma and leukemia did not increase the frequency of Treg cells." (PMID 31058083, 2019). "In the present study, we performed a comprehensive comparison between HHLA2 and PD-L1 in terms of the expression pattern, clinical relevance and their associations with tumor infiltrating CD3+, CD8+, CD4 + Foxp3+, CD68+, CD163+ and CD20+ immune cells in a ICC cohort after curative resection." (PMID 30885276, 2019). "Finally, the effects of altering DNMT1 levels in T-cells seemed to affect tumor growth through alteration of methylation status of Foxp3 on promoter and CpG regions." (PMID 31006654, 2019). "This positive impact of FoxP3+ Tregs might be partially attributed to the down-regulation of a persistent inflammatory process, which could promote inflammation-driven tumor progression." (PMID 31546872, 2019). "Foxp3-expressing regulatory T (Treg) cells can suppress the activity of various types of immune cells and play key roles in the maintenance of self-tolerance and in the regulation of immune responses against pathogens and tumor cells." (PMID 31434282, 2019). "Furthermore, our results showed that IBC patients are characterized by a high frequency of the Treg (Foxp3+CD4+) subset representing 23% of total CD4+ T cells drained from the tumor microenvironment." (PMID 31145753, 2019). "Interestingly, patients with low tumor FOXP3 expression and high Treg count have a significantly worse overall survival." (PMID 31827925, 2019). "We thus hypothesized that the high expression of GPR15 in COAD can contribute to the homing and infiltration of FOXP3+ regulatory T cells (Tregs), which in turn boost the immunity response of the tumor and results in a better prognosis." (PMID 31835584, 2019). "Thus, Foxp3+Tbet+ Treg cells accumulate at the OPSCC tumor sites where they probably exert a suppressive effect that is strong enough to impede full type 1 effector T cell-mediated control of the tumor (i.e. spontaneous tumor regression)." (PMID 30658697, 2019). "It was suggested that Foxp3+CD4+ T cells might in fact help to prevent or delay inflammation-mediated tumour development, as supported by the presence of remarkably higher levels of anti-inflammatory IL-10 from the serum samples of NSCLC patient." (PMID 30944831, 2019). "However, the prognostic role of T-reg infiltration is tumor-dependent, and, among CRC patients, a higher number of tumor-infiltrating FOXP3+ T-regs predicts favorable outcome of CRC patients." (PMID 31756952, 2019). "To further explore the tumor microenvironment in GC, we have focused on intratumor FoxP3+ Tregs, in order to examine whether Tregs participate in the regulation of the tumor milieu." (PMID 31417548, 2019). "Indeed, flow cytometric analysis of tumor-infiltrating lymphocytes from XO ki mice revealed higher frequencies of Foxp3 regulatory T cell." (PMID 31659168, 2019). "Constitutive STAT3 activation in tumor-residing DCs reduces expression of MHC class II and costimulatory molecules, impairs the antigen-presenting function of DC and contributes to the expansion of tumor-infiltrating FOXP3+ T-cells and attenuates CD4+ Th cell responses." (PMID 31480382, 2019). "However, a higher gene expression of GZMA in the tumor infiltrating lymphocytes correlated with prolonged survival, and a lower expression of FoxP3 or PDL1 further improved the patients’ survival." (PMID 31756926, 2019).
tumor (continued). "The higher Lgr5 levels in GC tumors with a high number of intratumor FoxP3+ Tregs observed in our study indicated that intratumor FoxP3+ Tregs may influence Lgr5 expression in tumor tissue." (PMID 31417548, 2019). "In addition, we examined the level of CD4+, CD25+, and Foxp3+ in tumor regulatory T cells (Tregs) by flow cytometry on day 8 after the start of treatment." (PMID 31653838, 2019). "Moreover, the gradual upregulation of ST2 on tumor-isolated CD4+ FOXP3+ Tregs during intestinal tumorigenesis suggested an immune regulatory function of IL-33 for this disease." (PMID 31165767, 2019). "Also, the role of RUNX1 or RUNX3 should be explored in the differentiation of I IL-17+FOXP3+ T cells in association with mTOR, CNOT2, HIF-1α and RIF-4 that are involved in tumor progression and immune tolerance." (PMID 31815635, 2019). "Tumor infiltrative forkhead box P3-positive (FOXP3+) regulatory T cells (Tregs) might play a crucial role in the immune microenvironment of GC." (PMID 31174544, 2019). "To further address the question whether this correlation would lead to immunosuppression or anti-tumour immune responses, we looked at the correlation between IL-35+ cells and Foxp3+ T cells." (PMID 30956278, 2019). "However, IR also led to an increased number of tumor-infiltrating FoxP3+CD4+ Tregs, and consequently a significantly decreased ratio of CD8+ T/Tregs in the irradiated tumors (p < 0.05, Student’s T test)." (PMID 31704921, 2019). "FOXP3 is a specific T-reg marker that suppresses anti-tumor immune responses." (PMID 30867568, 2019). "A significant decrease in proliferating (Ki67+) CD3+CD8− T cells and FoxP3+(CD3+CD8−) regulatory T cells was observed in the tumor stroma after cisplatin and paclitaxel treatment, with increased rates of cytotoxic CD8+ T cells, including activated and CD8+Tbet+ T cells." (PMID 31616965, 2019). "However, high concentration of IL-24 notably down-regulated FoxP3 mRNA relative level in both peripheral and tumor-infiltrating CD4+ T cells (Tukey tests, P < 0.0001)." (PMID 31921658, 2019). "Immunosuppression by tumor cells may partially be mediated through FoxP3+ regulatory T cell (T-reg) recruitment via tumor-secreted chemokines as shown in an ex vivo study." (PMID 30941125, 2019). "Additionally, miR-146, miR-7 and miR-155 induced by FOXP3 act as a tumor suppressor in breast and prostate cancers." (PMID 31815635, 2019). "It has been suggested that the role of FoxP3+ Tregs is influenced by tumor sites, molecular subtypes, and tumor stage, although related mechanisms are currently unknown." (PMID 31639056, 2019). "As described in murine tumor tissues, in IL-30NegPC samples, the lack of IL-30 in both cancer and infiltrating leukocytes was associated with a scanty to absent Foxp3+Treg cell content and a distinct TIA-1+CD4+T cell infiltrate." (PMID 31366386, 2019). "In addition, the percentage of Treg increased and the CD8+/Treg (CD4+FoxP3+) ratio was reduced in the residual tumor." (PMID 31780645, 2019). "The effects of CCL20 on Tregs may be to recruit existing FOXP3+ Tregs to tumor sites and inducing the expansion of retained Tregs, thereby synergistically carrying out immunosuppression." (PMID 31852159, 2019). "Moreover, hypoxia induces the recruitment of Tregs to the tumor microenvironment through CCL28 expression on tumor cells and the expression of Foxp3, thereby promoting intratumoral immune suppression." (PMID 31083487, 2019). "Lastly, intra-tumor infiltration of Tregs (CD3 + CD4 + FOXP3) was also disrupted by SR9243." (PMID 31863071, 2019). "Crucial to the generation of Treg cells are IL-2 and TGF-β, the latter particularly important as it directly induces the expression of FOXP3 (the master “identity factor” of Treg cells) via Smad factors binding to FOXP3 promoter, both of which abound in the tumor milieu." (PMID 30959898, 2019).
tumor (continued). "In addition, markers expressed at the tumor stroma (FOXP3 and CD8) or epithelial compartments (PR and insulinlike growth factor type 1 receptor) had no noticeable difference." (PMID 31348505, 2019). "Tumor‐infiltrating Foxp3 + Treg cells were positively correlated with tumor‐infiltrating DC2s." (PMID 31631566, 2019). "Also, FoxP3+ Treg infiltration in the IT compartment correlated with tumor p16 status (Mann-Whitney test, p = 0.007) and the majority of p16+ tumors was located in the oropharyngeal region (Kruskal-Wallis test, p = 0.001)." (PMID 30781400, 2019). "Thus, correlations between platelet count and five types of tumor infiltrating immune cells (CD3+ T cells, CD8+ cytotoxic T cells, FoxP3+ regulatory T cells, Tryptase+ mast cells, Elastase+ neutrophils) in different tumor locations were analyzed." (PMID 31196200, 2019). "A gene correlation analysis suggested a biological role of MS4A1/CD20-positive cells in antigen presentation, immune cell differentiation and T cell activation, further supported by multiplex IHC demonstrating that these cells interacted with both CD8- and FOXP3-positive cells in tumor tissue." (PMID 30879106, 2019). "AIRE is also involved in the development of tumor-associated Foxp3 + regulatory T cells (Tregs), which do not respond to tumor-specific antigens." (PMID 31641374, 2019). "Therefore, targeting this unique population of IL-17A+FoxP3+ T cells has the potential to restore effective anti-tumor immunity." (PMID 31681327, 2019). "However, only CD45RO+ TILs in the invasive margin area (p = 0.018) and FOXP3+ TILs in the central tumor area (p = 0.009) were statistically different among patients with low-, intermediate-, and high risks in this study." (PMID 31616592, 2019). "Additionally, higher FoxP3 infiltration in the stroma around the tumor was shown to predict a shorter recurrence free survival post-BCG treatment for NMIBC." (PMID 31824850, 2019). "Notably, the TbethiFoxp3hi Tregs expressed higher levels of helios, CTLA-4 and Ki67 than the Tbet– Foxp3+ Tregs, suggesting that they have been stimulated and activated in the tumor microenvironment." (PMID 30658697, 2019). "In addition, immunohistochemistry results showed that FOXP3 expression in the tumor tissues of CRC patients with neoadjuvant therapy (Folfox therapy) was higher than that without neoadjuvant therapy." (PMID 31395078, 2019). "Furthermore, our results indicate that NMIBC induces accumulation of Treg cells around the tumor tissue because the percentage of Foxp3+ cells among the CD3+ cells in TURBT specimens was higher than that in normal bladder tissue." (PMID 30261082, 2018). "FOXP3 has been previously identified as a tumour suppressor by our lab and others." (PMID 29963231, 2018). "Interestingly, when comparing the two tumor models the infiltration of FOXP3-positive cells into the tumor mass seems more prominent in the RG2 tumors compared to NS1." (PMID 29492202, 2018). "On day 28, the expression level of Foxp3 was found to be similar to control tumor-bearing mice." (PMID 30037009, 2018). "FOXP3 can suppress tumor growth, by regulating the expression of miR-146a/b11." (PMID 29549328, 2018). "We have identified an intriguing change in the DNA methylation status of the CNS2 locus of Foxp3 in the Nrp1-deficient Tregs from the tumor microenvironment but no loss in Foxp3 expression." (PMID 30400822, 2018). "Such patients displayed increased galectin-9-positive tumor cells and FOXP3+ lymphocytes, whereas the TIM-3+ lymphocytes were decreased in the tumor microenvironment compared with primary NPCs, suggesting that the galectin-9–TIM-3 pathway mediates immune escape by NPCs." (PMID 29389859, 2018). "Considering that Tregs within the tumor microenvironment might significantly suppress local antitumor immune responses, increased presence of Foxp3+ T cells in peripheral blood or tumor tissues have been associated with negative prognoses for various cancers." (PMID 29499656, 2018).
tumor (continued). "Additionally, representative material was investigated for markers of immune response or suppression, including CD4, CD8 and FOXP3, to attempt to visualize infiltration of immune cells into the tumor environment." (PMID 29492202, 2018). "Interestingly, CD8 and FoxP3 pixel counts were much higher in stromal areas than in tumor areas, in both hrHPV− and hrHPV+ tumors." (PMID 29942303, 2018). "Cells positive for both Foxp3 and CD3 (Foxp3+ T cells) were detected mainly in the tumor stroma." (PMID 30261082, 2018). "Thus higher levels of Foxp3+ Tregs correlate with more rapid tumour development in both control and Krt76−/− mice." (PMID 30143634, 2018). "The most direct evidence for hypoxia providing a tolerogenic tumor microenvironment for Tregs is the fact that hypoxia-driven HIF-1α strongly increases the expression of forkhead box P3 (Foxp3), which is a distinct marker and a master regulator in the development and function of Tregs." (PMID 30061885, 2018). "Furthermore, we show that PRP treatment decreased Foxp3 expression in H22 malignant tumors, where it simulated Tregs and inhibited immune escape of tumor cells, reducing the development of malignant ascites." (PMID 29735884, 2018). "In addition, CD39+ Treg in the tumor have higher density of intracellular Foxp3 than CD39− Treg, indicating a higher level of differentiation and activity." (PMID 30651930, 2018). "Although not significant due to high animal to animal variation, a strong tendency toward an increased amount of CD4+FOXP3+ T cells expressing the CD8α activation marker was observed in the tumor when compared with circulating blood (mean values: 16.0 and 2.1%)." (PMID 29930558, 2018). "Moreover, by ChIP-seq assay, we found that the differentially FOXP3-bound genes are involved in tumor development and metastasis." (PMID 29549328, 2018). "In tumor microenvironment, population of Foxp3+Treg cells may indicate poor prognosis as they provide protection to tumor cells against tumor-infiltrating lymphocytes." (PMID 30400642, 2018). "Furthermore, consistent with our previous results, IL-17A was found to be significantly increased within the CD4+Foxp3− tumor infiltrated lymphocytes, suggesting that these ex-Foxp3 TH17 cells maintain their ability to produce pro-inflammatory cytokine." (PMID 30413714, 2018). "Assessed GBC tumor samples (n = 77) were poorly infiltrated by Foxp3+ T cells." (PMID 29499656, 2018). "Besides, tumor-infiltrating Foxp3+LAG-3+Tregs secrete a higher level of immunosuppressive cytokines IL-10 and transforming growth factor-β (TGF-β) to collectively magnify Tregs activity." (PMID 30603054, 2018). "Based on our previous finding that FOXP3 can exert its tumour suppressive activity in part by regulating expression of miR-155, we investigated whether regulation of this microRNA further contributes to the regulation of ZEB2 by FOXP3." (PMID 29963231, 2018). "Therefore, an important question is how the tumor-suppressive function of wild-type FOXP3 is negated in these cancers." (PMID 29549328, 2018). "In addition, a study on patients with hepatocellular carcinoma showed that NKT-like cells in tumor tissue expressed FOXP3 and lost expression of IFN-γ and perforin compared with NKT-like cells in non-tumor tissue." (PMID 29535734, 2018). "We observed that CD3+ (a marker of T cells), CD8+ (a marker of cytotoxic T-cells), CD4+ (a marker of TH cells) and Foxp3+ (a marker of regulatory T cells) were negatively correlated with tumor size suggesting that most important is the T-cell immune response, lower is tumor grow." (PMID 30687269, 2018). "The enrichment of Tregs in tumours could be induced by the conversion of FOXP3- T cells into FOXP3+ T cells in the presence of TGFβ1 and retinoic acid." (PMID 30417146, 2018).